MITF (melanocyte inducing transcription factor)
Diseases named in the same sentence as MITF in open-access papers (continued):
Sharing a sentence is not in itself a finding about the gene and the disease.
breast carcinoma (29 papers, 2008 to 2026). "In another study, the microphthalmia-associated transcription factor (MITF) was found to be activated through O-GlcNAcylation by O-GlcNAc transferase (OGT) in breast cancer cells resistant to palbociclib." (PMID 40244377, 2025). "This notion aligns with recent research that highlights elevated MITF expression in basal breast cancer patients, wherein its abundance is linked to unfavorable prognosis." (PMID 37886470, 2023). "Our investigation involving clinical samples has revealed a noteworthy observation – the administration of palbociclib leads to an upregulation in the expression of MITF and its associated gene set in breast cancer patients." (PMID 37886470, 2023). "Encouraged by MITF’s prognostic value in basal breast cancer patients, we directly examined the functional impact of loss of MITF in basal breast cancer cells by transducing MDA-MB-436 cells with inducible MITF shRNAs followed by RNA-seq." (PMID 31554806, 2019). "Using high-throughput combinatorial drug screening and genomic sequencing, we find that the microphthalmia-associated transcription factor (MITF) is activated via O-GlcNAcylation by O-GlcNAc transferase (OGT) in palbociclib-resistant breast cancer cells and tumors." (PMID 38961064, 2024). "Our clinical studies contribute crucial evidence to support the proposition that MITF is pivotal in orchestrating resistance to CDK4/6i among breast cancer patients." (PMID 38961064, 2024). "This patient-specific data is both exhilarating and promising, which indicated that the elevated MITF expression is crucial for palbociclib resistance in breast cancer." (PMID 38961064, 2024). "Our clinical studies contribute crucial evidence to support the proposition that MITF-mediated pathways are pivotal in orchestrating resistance to CDK4/6i among breast cancer patients." (PMID 37886470, 2023). "Collectively, these results suggest that MITF inhibitor ML329 is able to overcome palbociclib resistance in breast cancer cells." (PMID 37886470, 2023). "To investigate how MITF regulates palbociclib resistance in breast cancer cells, we performed MITF ChIP-seq in MCF-7 and MCF-7 PR cells." (PMID 37886470, 2023). "During an important gene expression study of freshly resected human breast cancer specimens, the tumors expressed a group of genes (including MITF) that are expressed in melanocytic lineage cells." (PMID 36045272, 2022). "Together, these results validate the predictions made by PSIONIC on MITF activity and gene regulation in basal breast cancer." (PMID 31554806, 2019). "In another previous study, we identified the same upstream effectors (ERBB2, RABL6, FOXM1 and MITF) to be the most effected by palbociclib treatment in the MDA-MB-231 breast cancer cells, reducing colony formation, cell migration and viability." (PMID 31835892, 2019). "In analogy, we identified MYC enrichment at the identical site in the CDK7 promoter in various ChIP-seq data sets from breast cancer and B-cell malignancies suggesting that both MITF and MYC are able to directly transactivate CDK7." (PMID 30651597, 2019). "Collectively, these findings not only shed light on an innovative regulatory mechanism governing MITF’s activity and its role in palbociclib resistance but also provide a potential therapeutic strategy for effectively managing palbociclib-resistant breast cancer patients." (PMID 38961064, 2024). "Moxifloxacin (another quinolone) can contribute to S-phase arrest and the induction of apoptosis by cisplatin in pancreatic cancer through ERK activation, inhibit tumor growth or promote apoptosis in breast cancer by interacting with the Mcl-1 and MITF proteins." (PMID 38926655, 2024). "Thus, MITF appears to play an important role in regulating palbociclib resistance in CDK4/6i resistant breast cancer cells." (PMID 37886470, 2023).
breast carcinoma (continued). "Given that palbociclib induces cell cycle arrest and senescence as a primary mechanism to impede cell growth, we postulate that O-GlcNAc-MITF assumes a crucial role in modulating palbociclib resistance through senescence in breast cancer patients undergoing CDK4/6i therapy." (PMID 37886470, 2023). "Thus, O-GlcNAcylation at S49 of MITF plays a critical role in the regulation of palbociclib resistance in breast cancer cells." (PMID 37886470, 2023). "To further explore the role of MITF in the regulation of palbociclib resistance in breast cancer, we created a MITF signature geneset by overlapping proteins that interact with MITF (mass-spec analysis) and genes that are known to be associated with MITF function (PahtwayNet analysis)." (PMID 37886470, 2023). "Thus, MITF inhibition overcomes palbociclib resistance by activating senescence in resistant breast cancer cells." (PMID 37886470, 2023). "Thus, our cell-based studies and clinical evidence indicate that the CREB-dependent pathway plays an important role in the regulation of MITF-mediated palbociclib resistance in breast cancer cells." (PMID 37886470, 2023). "In the next step, we verified whether the observed MITF downregulation could affect breast cancer cell viability and proliferation." (PMID 36045272, 2022). "We demonstrated for the first time that the observed effects of MFLX on MDA-MB-231 breast cancer cells (growth inhibition and apoptosis induction) could be related to the drug’s ability to interact with MITF and Mcl-1 proteins." (PMID 36045272, 2022). "Our findings from the current study are concordant with our previously published work on transcription factors such as ERBB2, RABL6, FOXM1 and MITF which are most effected by palbociclib treatment in MDA-MB-231 breast cancer cells, reducing colony formation, cell migration and viability." (PMID 34565361, 2021). "Thus, we next sought to functionally validate PSIONIC-predicted MITF activity in basal breast cancer cells." (PMID 31554806, 2019). "The microphthalmia-associated transcription factor (MITF) is activated through O-GlcNAcylation by the O-GlcNAc transferase (OGT), which facilitates its translocation to the nucleus, thereby inhibiting senescence in palbociclib-induced breast cancer drug-resistant cells." (PMID 41583504, 2026). "Therefore, targeting MITF is a potential strategy for managing CDK4/6i-resistant breast cancer." (PMID 40244377, 2025). "To further validate whether increased MITF levels are a critical factor regulating palbociclib resistance in breast cancer, we examined the expression of MITF in a group of PDX lines, which consisted of 7 palbociclib-sensitive samples and 7 palbociclib-resistant samples." (PMID 38961064, 2024). "To further validate whether increased MITF levels are a critical factor regulating palbociclib resistance in breast cancer, we examined the expression of MITF-mediated pathway in a group of PDX lines, which consisted of 7 palbociclib-sensitive samples and 7 palbociclib-resistant samples." (PMID 37886470, 2023). "Collectively, these findings not only shed light on an innovative regulatory mechanism governing MITF's activity and its role in palbociclib resistance but also inform the development of a novel therapeutic strategy for effectively managing palbociclib-resistant breast cancer patients." (PMID 37886470, 2023). "Following the literature review, the current study is the first that determines the role of MITF and Mcl-1 proteins in the MFLX-induced cellular and molecular cascade underlying the drug’s cytotoxic and pro-apoptotic effect on triple-negative MDA-MB-231 breast cancer cells." (PMID 36045272, 2022). "Furthermore, the presented results suggest that MITF and Mcl-1 proteins could be considered as the target in the therapy of breast cancer." (PMID 36045272, 2022).
breast carcinoma (continued). "The objective of the present study was to verify whether the interaction between moxifloxacin (MFLX), one of the fluoroquinolones, and MITF/Mcl-1 protein, could affect the viability, proliferation, and apoptosis in human breast cancer using both in silico and in vitro models." (PMID 36045272, 2022). "Hence, our data suggest MITF might may play tumor-promoting roles in vivo by regulating the crosstalk of basal breast cancer cells with their tumor microenvironment." (PMID 31554806, 2019). "Breast cancer suppressor candidate-1 (BCSC-1) could down-regulate MITF by binding to SOX10." (PMID 22912767, 2012). "In this study, we have discovered a OGT-MITF axis that plays a crucial role in regulating MITF transcriptional activity and conferring resistance to CDK4/6 inhibitors in breast cancer." (PMID 38961064, 2024). "In this study, we have discovered a novel OGT-MITF-mediated pathway that plays a crucial role in regulating MITF transcriptional activity and conferring resistance to CDK4/6 inhibitors in breast cancer." (PMID 37886470, 2023). "Molecular docking analysis (in silico), fluorescence image cytometry, and Western blot (in vitro) techniques were applied to assess the contribution of MITF and Mcl-1 proteins in the MFLX-induced anti-proliferative and pro-apoptotic effects on the MDA-MB-231 breast cancer cells." (PMID 36045272, 2022). "In addition to MITF, other amplified and overexpressed genes are HER2 in 15%–20% of invasive breast carcinomas, MYC in 15-20% of breast cancer and several hematological malignancies, EGFR in squamous cell carcinomas, MDM2 in several cancer type." (PMID 31217906, 2019). "However, MITF protein was not expressed in MDA-MB-435 cells but mRNA expression was detected in other breast cancer cell lines, such as MCF-10A, MCF-7, SKBR3, and U87 and D54 glioblastoma cell lines." (PMID 29636110, 2018). "However, other authors suggested that cytoplasmic MITF staining might not be specific since it was observed in some clear cell sarcomas (which show evidence of melanocytic differentiation) but also breast cancer samples that were non-melanocytic." (PMID 37240204, 2023).
Tietz syndrome (22 papers, 2009 to 2025). Tietz syndrome is a genetic hypopigmentation and deafness syndrome characterized by congenital profound bilateral sensorineural hearing loss and generalized albino-like hypopigmentation of skin, eyes and hair. "Mitf+/Mi-wh mice are a model for human deafness-pigmentation syndromes, Waardenburg syndrome type 2a, and Tietz syndrome, caused by mutations in MITF gene and characterized by profound deafness along with melanocyte deficiency." (PMID 40674144, 2025). "MITF mutations are also observed in Tietz syndrome (albinism‐deafness syndrome) (Smith, Kelley, Kenyon, & Hoover, 2000)." (PMID 31960627, 2020). "A total of more than forty MITF mutations have been verified to be disease-causing in patients with either the Waardenburg’s syndrome type 2)WS2) (OMIM#193510) or the Tietz syndrome (OMIM #103500, 12]." (PMID 31898538, 2020). "To date, more than 54 disease‐causing mutations have been identified in MITF gene in patients with WS2 or Tietz syndrome." (PMID 33045145, 2020). "Genetic conditions affecting melanocyte biology, including Waardenburg Type II syndrome and Tietz syndrome (caused by mutations in MITF and SOX10), are also characterised in part by premature hair greying and, as with physiological hair greying, the greying is associated with a loss of melanocytes." (PMID 25670789, 2015). "A mutation at the same residue in the human MITF protein leads to Tietz syndrome, which is characterized by a more generalized depigmentation and profound obligate hearing loss compared to the slightly milder Waardenburg syndrome 2A, which is caused by many other mutations in the human MITF gene." (PMID 22511888, 2012). "Microphthalmia-associated transcription factor (MITF) is a central protein in the transcriptional regulation of tyrosinase and thereby melanogenesis, as demonstrated by its role in Waardenburg syndrome type 2 and Tietz syndrome." (PMID 19505344, 2009). "Up to date, at least 54 MITF gene mutations have been identified in WS2 and Tietz syndrome ("The Human Gene Mutation Database at the Institute of Medical Genetics in Cardiff," 2019 Oct 13)." (PMID 33045145, 2020). "The German White Fleckvieh is a useful large animal model to study human Tietz syndrome and the MITF transcription factor network." (PMID 22174915, 2011). "In humans, MITF is implicated in the development of WS2, Tietz syndrome, and COMMAD syndrome." (PMID 39457382, 2024). "Tietz syndrome (TS) (OMIM 103500) is a more severe form of WS2A, the characteristics of which are profound congenital deafness and generalized hypopigmentation of skin, hair, and eye that is transferred in an autosomal dominant manner with heterozygous mutations within the MITF gene." (PMID 34544414, 2021). "Some individuals with Tietz syndrome (OMIM: 103500), a genetic disorder marked by severe deafness and an overall lack of pigmentation, have also been shown to carry MITF mutations." (PMID 39457382, 2024).
renal carcinoma (20 papers, 2010 to 2025). A carcinoma arising from the epithelium of the renal parenchyma or the renal pelvis. "A recent study showed that renal carcinoma is associated with MITF/TFE translocation during the later stages of disease, i.e., when there is lymph node involvement." (PMID 34208068, 2021). "Melanotic Xp11 translocation renal cancer is a rare tumor belonging to the family of microphthalmia-associated transcription factor (MiTF)/transcription factor E (TFE) neoplasms." (PMID 24735727, 2014). "The proposed cytological diagnosis was papillary renal cell neoplasm, morphologically corresponding to MiTF/TFE family translocation-associated renal carcinoma." (PMID 23819507, 2013). "Recently, MITF has also been shown to be crucial for renal pathology since MITF variants were shown to affect the progression of renal disease or influence the occurrence of renal carcinoma." (PMID 29240767, 2017). "We found that GPNMB expression, which is regulated by MiTF, was greatly elevated in renal cancer cells harboring either TFE3 translocations or FLCN inactivation." (PMID 21209915, 2010). "Additionally, silencing MITF in renal carcinoma cells reduces proliferation, induces cell cycle arrest at the S/G2 phases in vitro, and suppresses tumor development in vivo." (PMID 41168571, 2025). "Furthermore, it has been observed that knocking down MITF in renal carcinoma cells reduces cell proliferation and blocks cells in the S/G2 phases in vitro, inhibiting tumor formation in vivo." (PMID 40343114, 2025). "Interestingly, TFE3 depletion inhibited proliferation of a renal carcinoma cell line, whereas ectopic overexpression of MITF in the TFE3-depleted cells rescued proliferation." (PMID 32881934, 2020). "Although we did find three VUS’s in BAP1 in three families and a pathogenic variant in MITF in one family, pathogenic germline variants in BAP1, MITF or CDKN2B are not frequent causes of hereditary renal cancer in Denmark." (PMID 31034483, 2019). "The results of the study indicate that germline variants in BAP1, MITF and CDKN2B are not frequent in Danish families with suspected hereditary predisposition to renal cancer, and in the families of this study a possible genetic background of RCC is still unresolved." (PMID 31034483, 2019).
vitiligo (20 papers, 2014 to 2024). Generalized well circumscribed patches of leukoderma that are generally distributed over symmetric body locations and is due to autoimmune destruction of melanocytes. "An additional intrinsic abnormality in vitiligo melanocytes, compared to the normal counterpart, is the marked higher expression of the Microphthalmia-associated transcription factor (MITF), which is associated with a differentiated status." (PMID 36429011, 2022). "In contrast, LC3 depletion suppressed the expression of microphthalmia-associated transcription factor (MITF) and tyrosinase, resulting in decreased melanin content, which suggests that impaired autophagy may participate in the pathogenesis of vitiligo." (PMID 38690268, 2024). "In addition, the Wnt/β-catenin signaling pathway might be involved in the activation of microphthalmia-associated transcription factor (MITF) and melanin synthase in vitiligo." (PMID 35320978, 2022). "In a study that analyzed the serum and melanocytes of vitiligo patients, the inverse expression of miR-125-5b and MITF has been observed." (PMID 39735711, 2024). "Due to this prominent role, several studies have investigated the relationship between miRNAs and MITF in vitiligo pathogenesis." (PMID 39735711, 2024). "MITF staining also showed significantly more melanocytes in LS than in vitiligo (MC/1B: 0.008 ± 0.006 vs. 0.004 ± 0.005, p < 0.0001)." (PMID 37521337, 2023). "This study used qRT–PCR to confirm the levels of miR-125b-5p and MITF in serum and tissues from 17 vitiligo patients and 17 healthy individuals." (PMID 36438898, 2022). "miR-125b-5p affects vitiligo melanocyte biological behavior and melanogenesis by downregulating MITF expression." (PMID 36438898, 2022). "Immunohistochemical results indicated a significant decrease in MITF expressions from vitiligo patient tissues." (PMID 36438898, 2022). "In vitiligo melanocytes, we observed MITF gene overexpression, indicating the activation of the differentiation processes." (PMID 36429011, 2022). "The goal was to confirm the mechanism by which miR-125b-5p influences melanocyte biological behavior and melanogenesis in vitiligo by regulating MITF." (PMID 36438898, 2022). "In summary, the level of miR-125b-5p was upregulated, and MITF was downregulated in vitiligo tissues and serum." (PMID 36438898, 2022). "The expression of MITF is significantly decreased in lesion and perilesion skin sections of vitiligo." (PMID 32267311, 2020). "NB-UVB increased the expression of MITF and tyrosinase during melanocytic differentiation and is currently used in clinical vitiligo phototherapy." (PMID 29019940, 2017). "It is associated with ERK activation, which subsequently up-regulates MITF levels, offering a potential mechanism that could be targeted in the treatment of vitiligo." (PMID 38054639, 2024). "MITF expression was significantly downregulated in vitiligo patients." (PMID 36438898, 2022). "Therefore, this study was aimed at confirming the relationship between miR-125b-5p, MITF, melanocyte biological behavior, and melanogenesis to explore the potential mechanism and provide a new way to treat vitiligo." (PMID 36438898, 2022). "miR-125b-5p and MITF are abnormally expressed in vitiligo and may play a key role in the development of vitiligo." (PMID 36438898, 2022). "Finally, we have demonstrated that there is an increased number of MITF + CXCR3B+ melanocytes in the NL skin of vitiligo patients compared to healthy skin (P = 0.03)." (PMID 31097717, 2019). "PMPP, a synthetic chalcone derivative that targets MITF and tyrosinase, has been proposed for vitiligo treatment, as PMPP dose-dependently increases both tyrosinase and MITF activities." (PMID 37371141, 2023). "D206008 was found to increase the melanogenesis (melanin) concentration via the activation of the Akt/GSK-3ß/ß-catenin pathway, which links to an increase in MITF and TYR activity, as well as melanogenesis, suggesting a possible vitiligo therapy." (PMID 37371141, 2023).